SUV39H1 (SUV39H1 histone lysine methyltransferase)
Description:
Histone methyltransferase that specifically mediates trimethylation of 'Lys-9' of histone H3 (H3K9me3) using monomethylated H3 'Lys-9' (H3K9me1) as substrate. Also weakly methylates histone H1 (in vitro). H3 'Lys-9' trimethylation represents a specific tag for epigenetic transcriptional repression by recruiting HP1 (CBX1, CBX3 and/or CBX5) proteins to methylated histones. Mainly functions in heterochromatin regions, thereby playing a central role in the establishment of constitutive heterochromatin at pericentric and telomere regions (By similarity). H3 'Lys-9' trimethylation is also required to direct DNA methylation at pericentric repeats. SUV39H1 is targeted to histone H3 via its interaction with RB1 and is involved in many processes, such as repression of MYOD1-stimulated differentiation, regulation of the control switch for exiting the cell cycle and entering differentiation, repression by the PML-RARA fusion protein, BMP-induced repression, repression of switch recombination to IgA and regulation of telomere length. Involved in the maintenance of H3K9me3 mark following DNA replication, when histone marks are diluted: HP1 recognizes the preexisting H3K9me3 mark and serves as a platform to recruit SUV39H1 to modify the adjacent newly incorporated histones. Component of the eNoSC (energy-dependent nucleolar silencing) complex, a complex that mediates silencing of rDNA in response to intracellular energy status and acts by recruiting histone-modifying enzymes. The eNoSC complex is able to sense the energy status of cell: upon glucose starvation, elevation of NAD(+)/NADP(+) ratio activates SIRT1, leading to histone H3 deacetylation followed by dimethylation of H3 at 'Lys-9' (H3K9me2) by SUV39H1 and the formation of silent chromatin in the rDNA locus. Recruited by the large PER complex to the E-box elements of the circadian target genes such as PER2 itself or PER1, contributes to the conversion of local chromatin to a heterochromatin-like repressive state through H3 'Lys-9' trimethylation (By similarity). (Microbial infection) Plays a role in defense against mycobacterial infections. Methylates M.tuberculosis HupB on 'Lys-140', probably methylates HupB of M.bovis also. Methylation has an inhibitory effect on mycobacterial growth in the host. Macrophages expressing about 60% SUV39H1 are slightly more susceptible to M.bovis or M.tuberculosis infection. Chaetocin (an inhibitor of this enzyme) increases macrophage survival of M.tuberculosis. This protein inhibits biofilm formation by M.tuberculosis via 'Lys-140' trimethylation.
Synonyms: H3-K9-HMTase 1; KMT1A; SUV39H; MG44
Tractability: Small molecule: a high-quality ligand is known; it belongs to a druggable protein family. Antibody: UniProt places it where antibodies can reach, with high confidence; its Gene Ontology location is reachable by antibodies, with medium confidence. PROTAC: UniProt records ubiquitination sites on it; ubiquitination databases record sites on it; a small molecule that binds it is known.
Target class: Writer; Protein methyltransferase; Epigenetic regulator
Gene: Protein-coding gene on chromosome X (48,695,554 to 48,709,016, forward strand). Ensembl gene ENSG00000101945.
Subcellular location: Nucleus; Chromosome; Nucleus lamina; Nucleus, nucleoplasm; Chromosome, centromere; Cytoplasmic vesicle, phagosome lumen; Cell membrane
Pathways (Reactome):
Chromatin organization: PKMTs methylate histone lysines
Gene expression (Transcription): SIRT1 negatively regulates rRNA expression
Gene Ontology:
Molecular function: histone H3K14ub reader activity; histone H3K9 methyltransferase activity; histone H3K9 trimethyltransferase activity; histone H3K9me2 methyltransferase activity; histone methyltransferase activity; protein binding; S-adenosylmethionine-dependent methyltransferase activity; chromatin binding; histone H3 methyltransferase activity; transcription cis-regulatory region binding; RNA polymerase II transcription regulatory region sequence-specific DNA binding; zinc ion binding
Biological process: cellular response to glucose starvation; cellular response to hypoxia; DNA damage response; energy homeostasis; epigenetic programming in the zygotic pronuclei; heterochromatin formation; heterochromatin organization; negative regulation of cell cycle; negative regulation of DNA-templated transcription; negative regulation of transcription by RNA polymerase II; pericentric heterochromatin formation; rDNA heterochromatin formation; regulation of transcription by glucose; chromatin organization; circadian rhythm; negative regulation of gene expression, epigenetic
Cellular component: chromatin; chromatin silencing complex; chromosome; eNoSc complex; heterochromatin; nuclear lamina; nucleolus; nucleus; pericentric heterochromatin; plasma membrane; rDNA heterochromatin; condensed nuclear chromosome; nucleoplasm; chromosome, centromeric region; cytoplasmic vesicle; nuclear lumen; ribonucleoprotein complex
Homologues: Orthologues: chimpanzee SUV39H1 (100% identical), macaque SUV39H1 (99% identical), pig SUV39H1 (98% identical), dog SUV39H1 (98% identical), mouse Suv39h1 (95% identical), rat Suv39h1 (94% identical), rabbit SUV39H1 (94% identical), guinea pig SUV39H1 (90% identical), zebrafish suv39h1b (69% identical), zebrafish suv39h1a (63% identical), Drosophila melanogaster Su(var)3-9 (41% identical), Caenorhabditis elegans met-1 (21% identical), and 8 more. Paralogues in human: SUV39H2 (59% identical), EHMT2 (34% identical), EHMT1 (33% identical), SETDB1 (25% identical), ASH1L (23% identical), NSD1 (23% identical), NSD3 (22% identical), SETDB2 (22% identical), KMT2D (20% identical), NSD2 (20% identical), KMT2A (20% identical), KMT2C (20% identical), and 7 more.
Diseases named in the same sentence as SUV39H1 in open-access papers:
SUV39H1 is named in the same sentence as 96 diseases in open-access papers, as found by Europe PMC text mining. Sharing a sentence is not in itself a finding about the gene and the disease. The quoted sentences say what the papers report.
breast carcinoma (19 papers, 2010 to 2024). "For example, loss of SUV39H1 leads to an increase of E-cadherin expression by decreasing H3K9me3 marks at its promoter and ultimately inhibits breast cancer cell migration." (PMID 35101125, 2022). "The inhibition of Suv39H1 can prevent EMT in breast cancer through the depletion of H3K9me3 in the promoter region of E-cadherin." (PMID 38424632, 2024). "Using breast cancer as a model, our lab showed that the activation of REs by SUV39H1 inhibition synergized with anti-PD-1 immune checkpoint blockade (ICB) therapy in mice." (PMID 39456183, 2024). "This may be explained by the fact that EZH2 and SUV39H1 regulate gene expression through the transfer of methyl groups to amino acid residues of histones, and their positive regulation has been linked in previous studies to aggressive breast cancer and a poor prognosis for breast cancer survival." (PMID 38929688, 2024). "Recently, we showed that viral mimicry induced by SUV39H1 targeting increased the surface expression of NK cell ligand ULBP2 on breast cancer cells." (PMID 39456183, 2024). "Combination therapy of decitabine and PAS1-30nt-RNA, which directly binds to SUV39H1, effectively blocked breast cancer growth and metastasis in mice." (PMID 35307730, 2022). "For example, Snail was reported to inhibit transcription of E-cadherin by interacting with Suv39H1 (suppressor of variegation 3-9 homolog 1) in breast cancer." (PMID 31956363, 2020). "The expression level of SUV39H1 inversely correlates with stage, prognosis, and disease free survival in oral squamous cell carcinoma and breast cancer." (PMID 24564251, 2013). "In addition, downregulation of the histone methyltransferases EZH2 and SUV39H1, observed after exposure to the combination of SFN, GE, and BS, is associated with reduced susceptibility to breast cancer." (PMID 38929688, 2024). "We speculate that LncRNA HOTAIR promotes the proliferation and invasion/metastasis of breast cancer (BC) cells by targeting the miR-130a-3p/Suv39H1 axis." (PMID 35619625, 2022). "Studies have also shown that disruption of transcriptional repressor multi-molecular complex, HDAC1/DNMT1/SUV39H1, is associated with ERα transcriptional activation in ERα-negative breast cancer cells." (PMID 22662208, 2012). "Furthermore, they showed that knockdown of Suv39H1 restored E-cadherin expression by blocking H3K9me3 and DNA methylation and resulted in an inhibition of cell migration, invasion and metastasis of basal-like breast cancer." (PMID 23148692, 2012). "MLL1, G9a, SUV39H1, JMJD3, and EZH2 expressions are increased in glioblastoma multiforme, breast cancer cell, and human fetal lung epithelial cells under hypoxic microenvironment, respectively." (PMID 29449535, 2018). "We next measured the levels of signature genes whose protein products could be pharmacologically targeted in breast cancer lines (AURKB, SUV39H1, SUV39H2 and KDM4B)." (PMID 27863398, 2016).
lymphoma (13 papers, 2013 to 2025). A malignant (clonal) proliferation of B- lymphocytes or T- lymphocytes which involves the lymph nodes, bone marrow and/or extranodal sites. "Accordingly, mice harboring Suv39h1-deficient or proficient lymphomas typically entered a clinical CR in response to a single administration of CTX in vivo (i.e., all mice presented tumor-free at time-point 0 post CTX)." (PMID 32686676, 2020). "Notably, limited T-cell cytotoxicity was elicited by T-cells primed by drug-exposed Suv39h1-deficient lymphoma cells, underscoring the dependency of efficient T-cell priming specifically on the senescent and DC-like state switch, not mere chemotherapy exposure." (PMID 40159497, 2025). "Mutual regulation of target genes was also evident when we analyzed the chromatin of TIS lymphomas in the Suv39h1 restoration model by Assay for Transposase-Accessible Chromatin using sequencing (ATAC-seq)." (PMID 40159497, 2025). "Probing TIS control;bcl2 lymphomas compared to equally ADR-exposed Suv39h1–;bcl2 samples by GSEA unveiled strong skewing towards various myeloid gene sets, including DC and Mφ profiles, a facet shared with other TIS, OIS, PICS and VIS models." (PMID 40159497, 2025). "Consistent with the suppression of apoptosis by senescence, the loss of Suv39h1 and therefore of OIS competence renders NRas‐driven lymphomas responsive to apoptosis induction." (PMID 32981205, 2021). "There it was shown that knockout of the senescence-related histone methyltransferase Suv39h1 accelerated Myc-driven lymphomagenesis with those lymphomas possessing an enhanced TGFβ signature reminiscent of the signature observed in Eμ-Myc lymphomas with loss of Bcor." (PMID 28262675, 2017). "A role for Suv39h1 in preventing Ras-induced lymphoma development in vivo has already been demonstrated, supporting the concept that Suv39h1/2-mediated regulation of ATM activity in a hypoxic context could halt tumorigenesis in response to oncogenic stress." (PMID 24268576, 2013). "Importantly, when we compared clinical outcome in the absence of an apoptotic block, mice bearing Suv39h1-deficient lymphomas had a much shorter TTR and a much higher fraction of lymphomas that relapsed within the observation period of 100 days." (PMID 32686676, 2020). "Besides, H3K9 methylation is critical to the initial step of lymphomagenesis, therefore its methyltransferase Suv39h1 may be important to lymphomas senesce after drug therapy." (PMID 27362259, 2016). "The researchers found that TIS-competent lymphomas, but not TIS-incompetent lymphomas lacking the H3K9 histone methyltransferase Suv39h1, exhibited increased glucose utilization and higher ATP production after senescence-inducing chemotherapy." (PMID 37649668, 2023). "After senescence-inducing chemotherapy, therapy-induced senescence (TIS) -competent lymphomas, but not TIS-incompetent Suv39h1– lymphomas, show increased glucose utilization and much higher ATP production." (PMID 34063570, 2021). "Importantly, when applying the LPS classifier as a TIS score, we found RES lymphomas, unlike the SENS lymphoma groups, to be strongly skewed toward a Suv39h1-deficient, hence, senescence-defective pattern in response to the 4-h CTX challenge in vivo." (PMID 32686676, 2020). "However defective heterochromatinization in mice lacking Suv39h1, the enzyme capable of tri-methylating histone H3K9, show increased susceptibility to lymphoma development in an Eμ-Nras model." (PMID 23936539, 2013).
glioma (11 papers, 2015 to 2025). A benign or malignant brain and spinal cord tumor that arises from glial cells (astrocytes, oligodendrocytes, ependymal cells). "Regarding prognosis, elevated SUV39H1 expression was linked to poorer outcomes across glioma grades in both the CGGA and TCGA datasets." (PMID 40059829, 2025). "Experimental data implicates histone H3 lysine (K) methyltransferases SETDB1 and SUV39H1 into glioma pathobiology, whereas linker histone variant H1.0 and H4K20me3 reportedly affect prognosis." (PMID 25602259, 2015). "To explore the clinical importance of SUV39H1, we analyzed its expression across glioma samples in the TCGA dataset." (PMID 40059829, 2025). "Clinically, high SUV39H1 expression correlates with poor glioma prognosis, supporting its relevance as a therapeutic target." (PMID 40059829, 2025). "SUV39H1 expression was positively correlated with the classic-like glioma subtype and markers such as NES and EGFR, with a lower correlation with mesenchymal-like markers like CD44 and CHI3L1." (PMID 40059829, 2025). "Analyses of The Cancer Genome Atlas (TCGA) and Chinese Glioma Genome Atlas (CGGA) verified the expression levels and prognoses associated with RUNX1/p-SMAD3/SUV39H1 target genes." (PMID 31754093, 2019). "In order to further examine the significance of SUV39H1 in gliomas progression, we inhibited its activity by using the chemical compound chaetocin." (PMID 25602259, 2015). "More recently, another study linked SUV39H1 with cancer stemness in diffuse intrinsic pontine gliomas, reporting that targeting SUV39H1 led to the downregulation of growth factor receptor signaling and stemness-related programs, resulting in inhibited glioma cell growth and increased cell death." (PMID 40059829, 2025). "Despite its tumor suppressor role in rhabdomyosarcoma, SUV39H1 promotes tumorigenesis in glioma." (PMID 31636512, 2019). "SUV39H1, an H3K9 methyltransferase, has been implicated in the progression of glioma." (PMID 31636512, 2019). "To further confirm whether SUV39H1 mediated epigenetic repression of miR-200c, we examined miR-200c expression after transfection of si-SUV39H1 to glioma cells." (PMID 31429770, 2019). "However, SUV39H2, a homologous enzyme of SUV39H1, is upregulated in many cancers, but it is still unknown whether it is upregulated in glioma." (PMID 31636512, 2019). "High SUV39H1 expression was seen in tumors with wild-type IDH and older patients and increased with tumor grade, peaking in grade IV gliomas, which include GBM (P = 0.0248)." (PMID 40059829, 2025). "We identified that miR-101 inhibits the expression of SUV39H1/2 and G9a but enhances the expression of PHF8 in glioma cells." (PMID 25829251, 2015). "Furthermore, SUV39H1 expression was positively correlated with SOX2 and OLIG2 expression in GBM samples from the TCGA and Chinese Glioma Genome Atlas (CGGA) databases." (PMID 40059829, 2025).
glioma (continued). "Thus, their targeting by siRNA significantly reduced proliferation of the glioma cell lines GOS-3 by inducing apoptosis and reduced cell migration and clonogenic ability, SUV39H1 being more influential in this regard." (PMID 25602259, 2015). "Yang et al51 reported that complex SUV39H1/CRL4B/HP1/DNMT3A promoted DNA methylation‐based epigenetic silencing, while Spyropoulou et al52 also showed that histone lysine N‐methyltransferases, especially SUV39H1, led to malignancy in gliomas and is a potential biomarker." (PMID 32281273, 2020). "In the GSE4290 database, we also found that SUV39H1 has a reverse correlation with HHIP, which indicates that SUV39H2 and SUV39H1 may have mutual compensatory effects on tumor growth and chemosensitivity in glioma." (PMID 31636512, 2019).